SIRT1 (sirtuin 1)
Diseases named in the same sentence as SIRT1 in open-access papers (continued):
Sharing a sentence is not in itself a finding about the gene and the disease.
kidney (33 papers, 2011 to 2025). "In this study, Sprague–Dawley (SD) rats were intracranially injected with either adeno-associated viral Sirtuin-1 (AAV-SIRT1) or AAV-sh_SIRT1 before undergoing transient middle cerebral artery occlusion (tMCAO)." (PMID 38767771, 2024). "Thus, baicalin protects against estrogen-induced cholestatic liver injury, and the underlying mechanism involved is related to activation of the Sirt1/HNF-1α/FXR signaling pathway." (PMID 32116682, 2019). "For example, nobiletin improves liver IR injury by activating SIRT-1/FOXO3A-mediated autophagy and mitochondrial biogenesis." (PMID 40718455, 2025). "The synthesis of SIRT1 in the diabetic kidney and its relationship with the urinary excretion of the molecule requires further research." (PMID 38540101, 2024). "Upregulation of SIRT1 attenuates ischemic liver injury and enhances mitochondrial recovery and autophagy." (PMID 34984826, 2022). "As SIRT1 acts upstream of PINK1, we also explored mechanisms underlying the effects of APN on upregulating mitophagy under diabetic lung IR conditions." (PMID 34602075, 2021). "In this study, we observed that SIRT1-mediated suppression of inflammation played a critical role in the protective activity of H2S in diabetic lung IR insult." (PMID 32695008, 2020). "In summary, our results demonstrated that baicalin protected EIC rats against cholestatic liver injury by restoring hepatic BA homeostasis and modulating the inflammatory response through activating the Sirt1/HNF-1α/FXR signaling pathway." (PMID 32116682, 2019). "In aging livers, restoring SIRT1 protein expression using adenovirus-SIRT1 vectors ameliorated chronic ethanol-induced liver injury and fibrosis, suggesting that aging exacerbates alcoholic liver injury via SIRT1 downregulation in both hepatocytes and HSCs." (PMID 40052151, 2025). "Activation of the SIRT1/Nrf2/HO-1 pathway not only enhances the antioxidant defense system but also fosters the crosstalk with autophagy pathways, as demonstrated by previous reports confirming its protective role in kidney injury models." (PMID 39770532, 2024). "All of these data indicated that GYY4137 might enhance Nrf-2/HO-1 signaling and maintain normal eNOS function and active form via SIRT1 activation, thus reducing oxidative stress, inflammation, and apoptosis in diabetic lung IR injury." (PMID 32695008, 2020). "The decrease in Sirt1 protein expression in the diabetic kidney may lead to inflammation through increased levels of acetylated-NF-κB (p65) and through the dysregulation of autophagy." (PMID 21949662, 2011). "Since mutual activation between FXR and Nrf2 has been reported, our findings suggest active roles of FXR and Nrf2 linking Sirt1 and bile acid metabolism, as well as their functional interplay in mediating the hepatoprotective actions of 18β-Glycyrrhetinic acid against cholestatic liver injury." (PMID 35624826, 2022). "Western blot results showed that ethanol feeding suppressed the levels of p-AMPKα, SIRT1, and PGC-1α, thereby promoting alcoholic fatty liver." (PMID 33994911, 2021). "Respectively employing transient models of middle cerebral artery occlusion (tMCAO) and oxygen and glucose deprivation/reoxygenation (OGD/R), the present study explored the role of SIRT1 in protecting mitochondrial structure and function following CI/R injury and the underlying mechanisms." (PMID 38767771, 2024). "Sirtuin 1 (SIRT1), a histone deacetylase, is involved in maintenance of genetic stability, inflammation, immune response, metabolism (energy-sensing molecule) and colorectal tumorigenesis." (PMID 32098999, 2020). "Third, we found evidence that, by upregulating SIRT1- PINK1-dependent mitophagy, APN might ameliorate mitochondrial dysfunction, thus reducing ROS production and inflammation, contributing to cell survival and ultimately preserving lung function during diabetic lung IR injury." (PMID 34602075, 2021).
heart disease (32 papers, 2012 to 2026). "Elevated acetylation in heart disease is associated with deceased SIRT1 expression." (PMID 41567643, 2025). "Likewise, the association of SIRT1 with alterations in QRS interval length in the UK Biobank matches the results of the enrichment analysis shown in ‘Hairball’, where SIRT1 was directly associated with heart diseases alongside 11 other genes from our study." (PMID 39195995, 2022). "Future research should integrate multi-omics approaches, single-cell transcriptomics, and precision medicine strategies to unlock the therapeutic potential of SIRT1 in cardiac diseases." (PMID 42196199, 2026). "This review summarizes recent findings regarding the physiological and pathological roles of SIRT1 related to heart diseases and explores the therapeutic potential of targeting SIRT1 and sirtuin family members for CVD treatment." (PMID 41567643, 2025). "ISM1 prevents aging-related cardiac dysfunction by promoting glycolysis and enhancing SIRT1 deacetylase activity, making it a promising therapeutic target for aging-related cardiac disease." (PMID 38300636, 2024). "Our study highlights the therapeutic potential of SIRT1-activating compounds in the treatment of human heart disease." (PMID 35260907, 2022). "The robust responses obtained with mIGF-I-induced SIRT1 activity suggested a potential mechanistic basis for strategies to improve the outcome of heart disease, and we were interested in further defining the molecular mechanisms involved in this process." (PMID 22691943, 2012). "Intimately tied to SIRT1 pathways are mammalian forkhead transcription factors (FoxOs) which can modulate cardiac disease to reduce oxidative stress, repair microcirculation disturbances, and reduce atherogenesis through pathways of autophagy, apoptosis, and ferroptosis." (PMID 37593239, 2023). "More importantly, by using cardiomyocyte‐specific Sirt1 knockout mice, we also indicate the essential role of Sirt1 in mangiferin‐mediated protective properties in MI; this helps us to better understand the effects of mangiferin in cardiac diseases." (PMID 33523605, 2021). "SIRT1 is one of the well-characterized stress adapters and epigenetic enzymes from the sirtuin family, known for its protective action in cellular processes such as inflammation, vascular aging, and cardiac diseases." (PMID 34743197, 2021). "Therefore, our findings suggest that endothelial CRIF1 plays an essential role in maintaining cardiac function, and that SIRT1 is a promising therapeutic strategy for endothelial OXPHOS dysfunction-induced cardiac diseases." (PMID 33430144, 2021). "As a bioactive compound derived from mango fruits, mangiferin could be used as a basis to design novel dietary approaches against ischaemic heart diseases, the action of which would be mediated through Sirt1 regulation of the epigenome." (PMID 33523605, 2021). "Regulation of the SIRT1–FOXO3a signaling pathway through some basic strategies may therefore play an active role in clinical heart disease." (PMID 26446137, 2015). "In vitro and in vivo findings corroborated these cardio-protective effects of SIRT1, suggesting that SIRT1 activation might be of benefit for the treatment of cardiac diseases." (PMID 22691943, 2012). "Moreover, the heart protection and therapeutic effects of higenamine on heart disease are related to regulating LKB1/AMPKα/Sirt1, mediating the β2-AR/PI3K/AKT cascade, induction of heme oxygenase-1, suppressing TGF-β1/Smad signaling, and targeting ASK1/MAPK (ERK, P38)/NF-kB signaling pathway." (PMID 35082678, 2021).
liver (13 papers, 2016 to 2025). "Overall, our findings contribute to a deeper understanding of SIRT1's role in gastrointestinal tumor progression and its potential as a target for future clinical interventions." (PMID 41020376, 2025). "A cohort of 198 individuals diagnosed with gastrointestinal tumors and 66 healthy volunteers were enlisted to undergo plasma SIRT1 testing." (PMID 41020376, 2025). "Through the use of the TIMER database, we investigated the link between this gene and immune cell infiltration in order to discover the connection that exists between SIRT1 and the immunomodulation of gastrointestinal tumors." (PMID 41020376, 2025). "The present study compiles the most recent findings on SIRT1 in the context of gastrointestinal tumors and provides a comprehensive summary, with the aim of facilitating future research endeavors." (PMID 40567502, 2025). "This comparative analysis is important as it provides a comprehensive understanding of how SIRT1 functions differently across various gastrointestinal tumor types." (PMID 41020376, 2025). "By unraveling the complex mechanisms through which SIRT1 operates, we can pave the way for more effective and personalized treatments for gastrointestinal tumors." (PMID 40567502, 2025). "This review examines the dual roles of SIRT1 in gastrointestinal tumors." (PMID 40567502, 2025). "Up to now, there remains no consensus regarding the role of SIRT1 in gastrointestinal tumors." (PMID 40567502, 2025).
adenocarcinoma (12 papers, 2011 to 2025). A common cancer characterized by the presence of malignant glandular cells. "There is a report that lncRNA LINC00842 binds to acetylated PGC-1α, and thus prevents its deacetylation by silent information regulator factor 2-related enzyme (SIRT1) in human adenocarcinoma cell lines and adenocarcinoma tissue samples." (PMID 36768958, 2023). "In wild type KRAS/BRAF invasive adenocarcinomas with nuclear beta-catenin, increased c-MYC expression was associated with an up-regulation of SIRT1." (PMID 23045412, 2012). "Early studies using the TRAMP mouse model showed stable SIRT1 expression during early carcinogenesis but a significant increase in poorly differentiated adenocarcinomas, correlating with reduced levels of hypermethylated in cancer-1 (HIC1), a regulator of SIRT1." (PMID 39796040, 2024). "Conversely, invasive adenocarcinomas negative for nuclear beta-catenin did not reveal any substantial c-MYC and SIRT1 staining (data not shown)." (PMID 23045412, 2012).
retinopathy (9 papers, 2014 to 2025). "In addition, MMPs are involved in mitochondrial damage caused by reactive oxygen species (ROS), and the AMPK and sirtuin 1 signaling pathways in retinopathy." (PMID 33328998, 2020). "In order to highlight a unique targeted method to treat HR, we investigated the effects of FO as a protective agent on SIRT1/NLRP3 in Ang II-induced retinopathy." (PMID 38360728, 2024). "Here, we discovered that FO therapy decreased NLRP3 activation, retinopathy, and dysfunction while increasing SIRT1 expression." (PMID 38360728, 2024). "And we first demonstrated that the slighter retinal disorders in T2DM would be related to the activation of the ALDH2/SIRT1 pathway." (PMID 34725563, 2021). "However, SIRT1 expression is downregulated in degenerative and age-related conditions, such as retinopathies and diabetes-related disorders like DR." (PMID 40006077, 2025). "FO may mitigate Ang II-induced retinopathy and dysfunction via modulating the expression of SIRT1/NLRP3." (PMID 38360728, 2024). "Further studies are needed to examine in depth whether increasing levels of Sirt1 may serve as a potential therapeutic approach to treat or prevent retinopathy." (PMID 24416337, 2014). "Together these results indicate that although endogenous Sirt1 is important as a stress-induced protector in retinopathy, over-expression of Sirt1 or treatment with small molecule activators at the examined doses do not provide additional protection against retinopathy in mice." (PMID 24416337, 2014). "We next assessed the effect of SRT1720, a highly potent Sirt1 specific activator, in retinopathy." (PMID 24416337, 2014). "In this study we assessed whether over-expression of Sirtuin1 in retinal neurons and vessels achieved by crossing Sirt1 over-expressing flox mice with Nestin-Cre mice or Tie2-Cre mice, respectively, may protect against retinopathy." (PMID 24416337, 2014). "In this study we investigated whether upregulation of Sirt1 levels or activity via genetic and pharmacologic approaches might protect against retinopathy in a mouse model of OIR." (PMID 24416337, 2014). "In this study we asked whether over-expression of Sirt1 may be protective in retinopathy." (PMID 24416337, 2014). "In our study, we found FO enhanced SIRT1 expression and reduced NLRP3 activation and retinopathy and dysfunction in Ang II-treated mice and mRECs." (PMID 38360728, 2024). "Resveratrol can inhibit p65 acetylation, activate sirtuin 1, inhibit the MMP-9 signaling pathway, and reduce retinopathy." (PMID 33328998, 2020). "FO may improve SIRT1 expression and decrease NLRP3 activation in retinopathy and dysfunction brought on by Ang II, and the effects were consistent across both in vivo and in vitro models." (PMID 38360728, 2024). "In addition, small molecule Sirt1 activators resveratrol and SRT1720 were orally supplemented in wild type mice before and during induction of retinopathy to evaluate their potential effects." (PMID 24416337, 2014). "Previously we found that Sirtuin1 (Sirt1), a metabolically dependent protein deacetylase, regulates vascular regeneration in a mouse model of oxygen-induced proliferative retinopathy (OIR), as neuronal depletion of Sirt1 in retina worsens retinopathy." (PMID 24416337, 2014). "Retinopathy and dysfunction were lessened by MCC950 target-induced NLRP3 inflammasome activation, while overexpression of SIRT1 had the opposite impact on NLRP3 inflammasome activation, indicating that SIRT1 functions as an upstream regulator of NLRP3 activity." (PMID 38360728, 2024). "Although the overexpression system used herein allowed the transgenic Sirt1 mice to reach the desired moderate increase of Sirt1 (∼4-fold) in neuronal retina, a level similar to those that produced a protective effect in other mouse tissues, it was not optimal to alter the course of retinopathy." (PMID 24416337, 2014).
retinopathy (continued). "This difference of expression in cell specificity may also account for the lack of protective effects in Nes-Sirt1 mice, and suggest that cell specific expression of Sirt1 may play a role in determining directional regulation of blood vessel growth in retinopathy." (PMID 24416337, 2014).
psychiatric disorder (8 papers, 2017 to 2025). A disorder characterized by behavioral and/or psychological abnormalities, often accompanied by physical symptoms. "Accumulating evidence suggests an association between the SIRT1 gene and human psychiatric disorders." (PMID 28439078, 2017).
bacterial infection (7 papers, 2013 to 2022). "We have shown previously that celecoxib in combination with ampicillin limits intracellular bacterial infection in macrophages by activating host SIRT1." (PMID 28533769, 2017). "Therefore, we evaluated the role of SIRT1 in the combinatorial efficacy to treat bacterial infection." (PMID 24950067, 2014). "Although SIRT1 was initially shown to have little influence on the regulation of mortality in Gram-negative endotoxemia or Gram-positive bacterial infection, a subsequent study demonstrated its involvement in models of several bacterial infections, including Helicobacter pylori infection." (PMID 36139497, 2022). "Given the emerging medicinal potential of this molecule, we studied its role in host innate defense and have demonstrated that therapeutic suppression of SIRT1 might be accomplished with limited effects on the host myeloid cell response to bacterial infections." (PMID 24386389, 2013). "Myeloid SIRT1 expression does not change mortality in gram-negative toxin-induced shock or gram-positive bacteremia, suggesting that therapeutic suppression of SIRT1 may be done safely without suppression of myeloid cell-specific immune responses to severe bacterial infections." (PMID 24386389, 2013).
brain diseases (7 papers, 2018 to 2026). "Thus, SIRT1 could be a promising pharmacological target for age-associated brain disorders, warranting more robust translational studies to validate these findings in humans." (PMID 41934491, 2026). "Moreover, Sirt1 also plays a protective role against neuroinflammation in brain disease." (PMID 30190704, 2018). "In chronic unpredictable mild stress mice, SIRT1 improves mitochondrial disorder and GABAergic function via SIRT1/PGC-1α/SIRT3 pathway, demonstrating their parallel contributions to neuroprotection against brain diseases." (PMID 40969935, 2025).
hematologic malignancies (7 papers, 2017 to 2026). "This opens an avenue for the potential translational exploitation of SIRT1 modulation as therapeutic target in this hematological malignancy." (PMID 41716403, 2026). "In some hematological malignancies, miR34a is dysregulated and plays a role in the pathogenesis by repressing its target genes, such as SIRT1 and FOXP1." (PMID 28008152, 2017). "SIRT1 inhibition may also be an option in other hematologic malignancies that are plagued by drug resistance." (PMID 28978059, 2017). "In an in silico approach, we conducted an analysis in the GEPIA database, and we validated the results of the present systematic review when we observed that the SIRT1, SIRT3, SIRT5 and SIRT6 genes are also up-regulated in onco-hematological diseases such as DBLC when compared with normal tissues." (PMID 36230534, 2022). "Although this approach is not specific towards SIRT1, NAMPT inhibitors exhibit potent antitumor activity and acceptable safety profiles in preclinical models of hematologic malignancies." (PMID 37816710, 2023).
immune disorders (7 papers, 2019 to 2025). "Overall, the evidence points to a role for SIRT1 as a bridge between metabolism and inflammation, making it a potential therapeutic target in metabolic and immune diseases; however, the specific role and mechanisms involving SIRT1 in this promising field require further study." (PMID 39372420, 2024). "Moreover, the current literature has reported involvement of SIRT1 in systemic processes such as ageing, metabolism, diet, glucose tolerance, or immune disorders." (PMID 37175520, 2023). "When SIRT1 levels are reduced, CD8 + T cell glycolysis and cytotoxicity are enhanced, resulting in immune dysfunction." (PMID 36299860, 2022).
benign tumors (4 papers, 2020 to 2024). "However, considering the acute nature of our study, it is less likely that mechanisms mediated by SIRT1 may contribute the acute mitochondrial metabolic alterations seen in post-ischemic heart." (PMID 38216627, 2024).
mitochondrial disease (4 papers, 2018 to 2022). "First, although mitochondrial disease was considered as the essence of NAFLD, few studies have performed the regulatory relationship between SIRT-1/PGC-1a and mitochondrial biology in the disease." (PMID 33902605, 2021). "Furthermore, our findings support the idea that the induction of mitochondrial biogenesis, for instance by activating the SIRT1-and/or AMPK-dependent PGC-1α axis, or other mitochondriogenic pathways, could be a rational and potentially effective approach in the therapy of mitochondrial diseases." (PMID 30122554, 2018).
peripheral neuropathy (4 papers, 2022 to 2025). A disorder affecting the peripheral nervous system. "NaB further rescues neuronal mitophagy by blocking RELA-HDAC8 repression of Parkin, while the SIRT1 activator piceatannol (PCN) enhances both mitogenesis and mitophagy via SIRT1/PGC1α and SIRT1/PINK1/Parkin axes, alleviating peripheral neuropathy." (PMID 40866350, 2025).
respiratory disorders (4 papers, 2015 to 2022). "The association of SIRT1 with respiratory disorders has received attention in recent years." (PMID 36457607, 2022). "Findings contributed to the hypothesis that COPD could be considered a disease of accelerated aging and underline the potential of SIRT1 as a valid therapeutic target to treat respiratory disorders sharing chronic inflammation." (PMID 30781849, 2019).